TAF12 (TATA-box binding protein associated factor 12)
Description:
The TFIID basal transcription factor complex plays a major role in the initiation of RNA polymerase II (Pol II)-dependent transcription. TFIID recognizes and binds promoters with or without a TATA box via its subunit TBP, a TATA-box-binding protein, and promotes assembly of the pre-initiation complex (PIC). The TFIID complex consists of TBP and TBP-associated factors (TAFs), including TAF1, TAF2, TAF3, TAF4, TAF5, TAF6, TAF7, TAF8, TAF9, TAF10, TAF11, TAF12 and TAF13. Component of the TATA-binding protein-free TAF complex (TFTC), the PCAF histone acetylase complex and the STAGA transcription coactivator-HAT complex.
Synonyms: TAF2J; TAFII20
Tractability: Small molecule: a structure with a bound ligand is known. PROTAC: UniProt records ubiquitination sites on it; ubiquitination databases record sites on it; its protein half-life has been measured.
Gene: Protein-coding gene on chromosome 1 (28,587,829 to 28,648,364, reverse strand). Ensembl gene ENSG00000120656.
Subcellular location: Nucleus
Pathways (Reactome):
Gene expression (Transcription): RNA Polymerase II Pre-transcription Events; RNA Polymerase II Promoter Escape; RNA Polymerase II Transcription Initiation; RNA Polymerase II Transcription Initiation And Promoter Clearance; RNA Polymerase II Transcription Pre-Initiation And Promoter Opening
Disease: HIV Transcription Initiation; RNA Polymerase II HIV Promoter Escape; Transcription of the HIV genome
Chromatin organization: HATs acetylate histones
Gene Ontology:
Molecular function: DNA binding; DNA-binding transcription factor binding; protein binding; RNA polymerase II general transcription initiation factor activity; transcription coactivator activity; TBP-class protein binding; protein heterodimerization activity
Biological process: DNA-templated transcription initiation; mRNA transcription by RNA polymerase II; positive regulation of transcription by RNA polymerase II; positive regulation of transcription initiation by RNA polymerase II; regulation of transcription by RNA polymerase II; RNA polymerase II preinitiation complex assembly; transcription initiation at RNA polymerase II promoter; positive regulation of DNA-templated transcription; regulation of DNA repair; regulation of DNA-templated transcription; regulation of RNA splicing; transcription by RNA polymerase II
Cellular component: nucleus; SAGA complex; transcription factor TFIID complex; transcription factor TFTC complex; nucleoplasm
Genetic constraint (gnomAD): Loss-of-function variants: 3 observed, 20.68 expected, observed/expected ratio (o/e) 0.15, 90% interval 0.065 to 0.38. The upper end of that interval is the gene's LOEUF score, 0.38, which puts it in group 1 of 6, group 1 being the genes least tolerant of losing a copy. Missense variants: 131 observed, 206.27 expected, observed/expected ratio (o/e) 0.64, 90% interval 0.55 to 0.73. Synonymous variants: 69 observed, 73.92 expected, observed/expected ratio (o/e) 0.93, 90% interval 0.77 to 1.14.
Homologues: Orthologues: chimpanzee TAF12 (99% identical), dog TAF12 (99% identical), pig TAF12 (99% identical), rabbit TAF12 (99% identical), guinea pig TAF12 (98% identical), rat Taf12 (97% identical), mouse Taf12 (96% identical), macaque TAF12 (92% identical), zebrafish taf12 (82% identical), tropical clawed frog taf12 (81% identical), Drosophila melanogaster Taf12 (52% identical), Caenorhabditis elegans taf-12 (33% identical).
Diseases named in the same sentence as TAF12 in open-access papers:
TAF12 is named in the same sentence as 15 diseases in open-access papers, as found by Europe PMC text mining. Sharing a sentence is not in itself a finding about the gene and the disease. The quoted sentences say what the papers report.
choroid plexus carcinoma (3 papers, 2019 to 2022). A malignant neoplasm arising from the choroid plexus. "TATA box-binding protein-associated factor 12 (TAF12) has been identified as an oncogene in choroid plexus carcinoma, but its role in glioma is poorly understood because of a lack of previous studies." (PMID 36551275, 2022). "(ii) Mouse/human genomic screenings searching for driver oncogenes of Choroid Plexus Carcinomas identified the syntenic NF-YC, TAF12 and RAD54L genes, with the formers having the greatest impact on tumor development." (PMID 31506469, 2019). "Recently, TBP-associated factor 12 (TAF12) has been shown to be important for the RAS-induced transformation properties of human colon cells and identified as an oncogene in choroid plexus carcinoma.To date, studies on the role of TAF12 in glioma have been very limited." (PMID 36551275, 2022).
colon carcinoma (2 papers, 2019 to 2022). "We performed ChIPseq using HCT116 colon carcinoma cells, identifying ~850 putative target genes associated with metabolism (e.g., Prdx5, Mdh1, Ahcy), transcription (Taf12, Tet2, histones), malignancy (Met, Blcap, Rras, Jag1, Gsk3a) and mitotic stability (Zbtb4)." (PMID 31059499, 2019).
acute myeloid leukemia (1 paper, 2022). Acute myeloid leukemia (AML) is a group of neoplasms arising from precursor cells committed to the myeloid cell-line differentiation. "Their study revealed that loss of TAF12 function could impair MYB activity and cause regression of acute myeloid leukemia (AML) in a mouse model." (PMID 36551275, 2022).
glioblastoma multiforme (1 paper, 2022). "Furthermore, the mRNA expression level of TAF12 was also apparently higher in glioblastoma multiforme (GBM) and relatively increased in low-grade glioma (LGG) compared with normal samples from TCGA and GTEx datasets based on GEPIA analysis." (PMID 36551275, 2022).
glioma (1 paper, 2022). A benign or malignant brain and spinal cord tumor that arises from glial cells (astrocytes, oligodendrocytes, ependymal cells). "Kaplan–Meier survival analysis showed that high TAF12 expression was associated with shorter overall survival among glioma patients, and multivariate Cox analysis identified TAF12 as an independent poor prognostic factor in patients with glioma." (PMID 36551275, 2022). "TAF12 is a potential independent prognostic factor for glioma, and these findings provide a foundation for further investigation of the potential role of TAF12 in immunotherapy." (PMID 36551275, 2022). "This study investigated the relationship of TAF12 expression with the clinicopathologic features of glioma cases, as well as its prognostic value and biological function, using large-scale databases and clinical samples." (PMID 36551275, 2022). "Due to the histopathological heterogeneity of glioma, the TAF12 mRNA expression data were analyzed according to WHO grade, histology, IDH1 mutation, and other features." (PMID 36551275, 2022). "We then performed bioinformatics analyses to explore the biological function and prognostic value of TAF12 in glioma." (PMID 36551275, 2022). "Here, we found that patients with different levels of TAF12 expression showed significant differences in the proportions of immune-infiltrating cells within glioma samples using ssGSEA and the CIBERSORT algorithm." (PMID 36551275, 2022). "We compared the transcriptional levels of TAF12 in glioma samples with those in normal samples from TCGA and GSE16011." (PMID 36551275, 2022). "To investigate the biological roles of TAF12 in glioma, we first identified DEGs between high and low TAF12 expression groups." (PMID 36551275, 2022). "Kaplan–Meier survival analysis demonstrated that higher TAF12 expression was correlated with shorter overall survival of glioma patients in both the discovery and validation sets." (PMID 36551275, 2022). "We demonstrated that TAF12 was significantly upregulated in glioma samples compared to normal tissues, and high TAF12 expression correlated well with malignant behaviors, such as high WHO grade and IDH wildtype status in glioma." (PMID 36551275, 2022). "Further in vitro and in vivo experiments examining the molecular functions of TAF12 in glioma will support the development of more accurate prognostic models for patients, which will allow more personalized therapies for gliomas." (PMID 36551275, 2022). "Semi-quantitative scoring of IHC staining showed that TAF12 was enriched in high-grade glioma (HGG), and TAF12 protein expression was positively associated with WHO grade." (PMID 36551275, 2022). "In the present study, we examined TAF12 gene expression and the clinicopathological characteristics in glioma cases using data from public databases and clinical samples from our institution." (PMID 36551275, 2022). "Multivariate Cox regression analysis showed that high TAF12 expression was an independent poor prognostic factor for glioma patients (hazard ratio = 1.41, 95% confidence interval, 1.18–1.68, p < 0.001)." (PMID 36551275, 2022). "Heatmaps showed infiltration of CD8+ T cells, macrophages, T helper (Th) cells and tumor-infiltrating lymphocytes (TILs) in glioma samples with high TAF12 expression, whereas fewer Th1_cells showed the opposite trend." (PMID 36551275, 2022). "Together these findings suggest that the high TAF12 expression can predict a high level of malignancy in glioma." (PMID 36551275, 2022). "The results from the two datasets demonstrated that TAF12 was significantly upregulated in glioma samples compared with normal samples." (PMID 36551275, 2022). "The prognostic value of TAF12 expression for gliomas was further confirmed in the two validation sets." (PMID 36551275, 2022). "Functional enrichment analysis revealed involvement of TAF12 in immune and inflammatory responses in glioma." (PMID 36551275, 2022).
glioma (continued). "Together the results of these gene enrichment analyses indicate that TAF12 likely participates in the malignant progression of glioma, particularly in the immune and inflammatory responses in glioma." (PMID 36551275, 2022). "Functional enrichment analyses revealed the involvement of TAF12 in a variety of cellular functions and signal regulation pathways related to the malignant progression of glioma, including many immune-related pathways." (PMID 36551275, 2022). "Meta-analysis further confirmed the relationship between TAF12 overexpression and worse prognosis in glioma patients." (PMID 36551275, 2022). "TAF12 mRNA expression and clinicopathologic characteristics of glioma cases were assessed in three public databases, and bioinformatics analyses were conducted to explore the prognostic value and biological functions of TAF12 in glioma." (PMID 36551275, 2022). "To further investigate the potential role of TAF12 in glioma in the present study, we first examined the transcriptional level of TAF12 and its relationship with the clinicopathological characteristics of glioma cases using data from multiple public databases and our clinical specimens." (PMID 36551275, 2022). "NK cells are a specialized immune effector cell type that plays a critical role in immune activation against abnormal cells, but unfortunately, in the present study, the level of activated NK cells in glioma samples was reduced in the high TAF12 expression group." (PMID 36551275, 2022). "Our findings lay a foundation for further mechanistic studies of TAF12 in glioma." (PMID 36551275, 2022). "Finally, meta-analysis of the three datasets confirmed the prognostic role of TAF12 expression in glioma, indicating that TAF12 may be a novel prognostic biomarker in glioma." (PMID 36551275, 2022). "Moreover, ROC curve analysis showed that TAF12 expression could predict 3- and 5-year survival of glioma patients with AUC values >0.7, which supports the use of TAF12 expression as a novel predictor of survival in glioma." (PMID 36551275, 2022). "Together, these findings demonstrated that TAF12 expression was a negative prognostic factor in glioma patients." (PMID 36551275, 2022).
leukemia (1 paper, 2021). A malignant (clonal) hematologic disorder, involving hematopoietic stem cells and characterized by the presence of primitive or atypical myeloid or lymphoid cells in the bone marrow and the blood. "It is also possible that leukemic gene expression by MYB involves additional transcriptional co-activators, such as TAF12, as part of the recently described TFIID-SAGA complex interaction, or other TAFs which have also been implicated in transcriptional co-regulation in leukemias." (PMID 33527899, 2021).
melanoma (1 paper, 2016). A malignant, usually aggressive tumor composed of atypical, neoplastic melanocytes. "In melanomas, TAFH RNAi induced the differential expression of TBP, TAF1, TAF2, TAF6, TAF10, and TAF12 ASVs." (PMID 27499390, 2016).
tumor (4 papers, 2011 to 2025). "lnc-TAF12–2:1 silencing resulted in a significant reduction in mouse growth, whereas its overexpression caused tumor development in vivo compared with the control group." (PMID 40297540, 2025). "On KEGG pathway analysis, the DEGs related to TAF12 expression were mainly enriched in focal adhesion, leukocyte transendothelial migration, cell cycle, antigen processing and presentation, apoptosis, and some tumor-associated signaling pathways such as the PI3K, Ras, and MAPK pathways." (PMID 36551275, 2022). "In summary, our data demonstrated that lnc-TAF12–2:1 was markedly up-regulated in urinary exosomes and tumor tissues of BCa patients and BCa cells." (PMID 40297540, 2025). "We found exosomal lnc-TAF12–2:1 up-regulated in urinary exosomes, tumor tissues of patients, and BCa cells." (PMID 40297540, 2025). "Capsuled in urinary exosomes and secreted by tumor cells, lnc-TAF12–2:1 was highly expressed in BCa patients and had a considerable diagnostic performance with an AUC of 0.854." (PMID 40297540, 2025). "Tumor tissues of cohort 4 were used to explore the correlation between the relative expression of lnc-TAF12–2:1 and miR-7847–3p." (PMID 40297540, 2025). "We first assessed the correlation between TAF12 expression and tumor infiltration levels of 22 types of TIICs." (PMID 36551275, 2022). "To verify these results, we randomly selected 28 patients for IHC analysis to detect the correlation between tumor grade and TAF12 protein expression." (PMID 36551275, 2022). "Additionally, we found that TAF12 expression was positively correlated with tumor grade." (PMID 36551275, 2022).
tumors of the CNS (1 paper, 2022). "Furthermore, because of an update to the classification system, we also evaluated the expression level of TAF12 according to the grading of adult diffuse gliomas in the 2021 5th edition of the WHO classification of tumors of the CNS." (PMID 36551275, 2022).
TAF12 also shares sentences with these, for which no sentence is quoted: bladder cancer (1 paper); cancer (1); colorectal (1); ischemia (1); low grade glioma (1); ovarian carcinoma (1).